BACE1 (beta-secretase 1)
Diseases named in the same sentence as BACE1 in open-access papers (continued):
Sharing a sentence is not in itself a finding about the gene and the disease.
Alzheimer disease (continued). "The dysregulation of BACE1AS is associated with upregulated BACE1 activity in several human disorders, including Alzheimer’s disease, Parkinson’s disease, heart failure, and MCI, indicating a potential influential role of BACE1AS in the progression of these diseases." (PMID 38543885, 2024). "As a result, blocking BACE1 activity may prevent 1 of the early pathogenic processes in Alzheimer’s disease." (PMID 39224568, 2024). "AMPK is highly expressed in neurons; AMPK activation (phosphorylation of AMPK at site Thr172) is increased in the cortex under DIO and then decreased after exercise, which is associated with reduced cortical BACE1 content, a hallmark of Alzheimer’s disease (AD)." (PMID 38464534, 2024). "Similar positive regulatory effects have been reported for the tumor suppressor gene PDCD4, which controls breast cancer progression, and the association of BACE1 with Alzheimer’s disease pathophysiology, where the stability of mRNAs was found to be promoted by their NATs." (PMID 37154775, 2023). "Moreover, CHL1 is a neural cell adhesion molecule and a close homolog of BACE1, the rate-limiting enzyme for the production of β-amyloid peptide linked to Alzheimer's disease (AD)." (PMID 36797805, 2023). "It is also involved in three different pathways and has interactions with three other target genes involved in Alzheimer’s disease and cholesterol, which allows for multiple ways to inhibit not only BACE1 but other target genes associated with cholesterol production and Alzheimer’s disease." (PMID 37444065, 2023). "β-Secretase (BACE1) is the vital enzyme in the pathogenic processes of Alzheimer's disease (AD)." (PMID 36494704, 2022). "Of note, the pattern of differently altered BACE1 and Ng levels in A+/T−/N− and A+/T+/N+ groups resulted in a stage-wise elevation of Ng/BACE1 ratios through the Alzheimer’s disease continuum and was more strongly associated with baseline memory performance and later decline than Ng or BACE1 alone." (PMID 36262371, 2022). "Moreover, several genetic variants were found to increase risk for neurodegenerative diseases, such as Alzheimer’s disease (rs4938369 in BACE1) or schizophrenia (rs6932590 in TRNAV27)." (PMID 35899193, 2022). "It was observed that BACE1 activity was significantly associated with amyloid-beta peptide levels and t-tau in mild cognitive impairment subgroups, suggesting its involvement in the pathogenesis of Alzheimer’s disease." (PMID 33578866, 2021). "Beta-secretase 1 (BACE1) enzyme is implicated in the pathophysiology of Alzheimer’s disease." (PMID 32140803, 2020). "BACE1 promotes A• production and is a neuropathological hallmark of Alzheimer's disease." (PMID 32323475, 2020). "It has been hypothesised that partial inhibition of BACE1 in individuals with a high risk of developing Alzheimer’s disease may be beneficial in preventing cognitive decline." (PMID 31547430, 2019). "Beta-site amyloid-precursor-protein cleaving enzyme 1 (BACE1) is the rate limiting protease in the production of the amyloid-beta peptide (Aβ), which is considered to be the causative agent in the pathogenesis of Alzheimer’s Disease (AD)." (PMID 30093858, 2018). "We provide evidence that BACE1-induced hypothalamic dysregulation causes systemic diabetes, which may explain the high comorbidity of diabetes and Alzheimer’s disease in ageing populations." (PMID 27138913, 2016). "Notably, the human sequence of the Swedish familiar Alzheimer disease mutation (APPswe) is used in almost all AD animal models as it serves as a better substrate for BACE-1, thereby increasing production of total Aβ and specifically 1-X Aβ peptides." (PMID 28105004, 2016). "Since complete loss of BACE1 activity has detrimental effects in BACE1−/− mice it seems likely that almost complete inhibition of BACE1 for treatment or prevention of Alzheimer’s disease could have mechanism based side-effects in humans." (PMID 25567526, 2015).
Alzheimer disease (continued). "Since BACE1 activity is known to cause Alzheimer's disease, it is essential to design a selective drug that could specifically target BACE1 over BACE2." (PMID 25254246, 2014). "Causes of Alzheimer’s disease (AD), one type of dementia, have been attributed to (i) degradation of the neurotransmitter acetylcholine by acetylcholinesterase (AChE) and butyrylcholinesterase (BChE), or (ii) accumulation of amyloid plaque formed during amyloidogenesis by β-secretase (BACE-1)." (PMID 34451608, 2021). "Thus, BACE1 may contribute to metabolic regulation; however, it remains to be established whether BACE1 mediates the association between type 2 diabetes and Alzheimer’s disease." (PMID 27138913, 2016). "The β-secretase BACE1 (β-site amyloid precursor protein (APP) cleaving enzyme 1) plays a central role in Alzheimer’s disease (AD), as it initiates the amyloidogenic processing of APP to form pathogenic amyloid β peptides (Aβ)." (PMID 41266616, 2026). "The β‐secretase BACE1 (β‐site amyloid precursor (APP) cleaving enzyme 1) is a major drug target for Alzheimer's disease (AD), as it catalyzes the first step in amyloid β (Aβ) generation, but has additional substrates and functions, in particular in the brain." (PMID 41310967, 2026). "The discovery of dual acetylcholinesterase (AChE) and β-secretase (BACE1) inhibitors remains a promising strategy against multifactorial Alzheimer's disease." (PMID 41603986, 2026). "The deficiency of RTN3 located in the endoplasmic reticulum increases the activity of BACE1 and promotes amyloid deposition in a mouse model of Alzheimer's disease; RTN3 thus showed its neuroprotective effect." (PMID 41578884, 2026). "Beta‐site APP‐cleaving enzyme 1 (BACE1), a critical rate‐limiting enzyme that synthesizes β‐amyloid peptide (Aβ), is an important marker of early pathological changes in Alzheimer's disease (AD)." (PMID 41144739, 2026). "The β-secretase BACE1 has become a prime target in Alzheimer’s disease (AD) therapy, because it drives the production of pathogenic amyloid β peptides." (PMID 41266616, 2026). "These are two brain-specific uncoupling proteins (SCL25A27 and SLC25A14) and three genes linked to Alzheimer Disease (PSEN1, PSEN2, and BACE1)." (PMID 40901366, 2025). "β‐secretase (BACE1) is instrumental in amyloid‐β (Aβ) production, with overexpression noted in Alzheimer's disease (AD) neuropathology." (PMID 39755927, 2025). "β-secretase 1 (BACE1) has been shown to contribute to Alzheimer’s disease (AD) through its cleavage on amyloid precursor protein (APP)." (PMID 40507910, 2025). "In summary, our study demonstrates the significant impact of Gnb5 on cognitive function and Aβ plaque deposition, elucidating the mechanisms by which it regulates BACE1, which is central to Alzheimer’s disease progression." (PMID 40587559, 2025). "Glutaminyl cyclase (GC), histone deacetylase (HDAC), and beta-site amyloid precursor protein cleaving enzyme (BACE-1) are involved in the progression of Alzheimer’s disease." (PMID 41103911, 2025). "In Alzheimer’s disease (AD), the β-secretase enzyme BACE1 cleaves the transmembrane amyloid precursor protein (APP)." (PMID 40429850, 2025). "The development of BACE-1 (β-site amyloid precursor protein cleaving enzyme 1) inhibitors is a crucial focus in exploring early treatments for Alzheimer’s disease (AD)." (PMID 40004143, 2025). "We investigated the immunological mechanisms and effects of berberine in the treatment of Alzheimer’s disease, revealing that berberine specifically binds to BACE1, one of the key targets in Alzheimer’s disease." (PMID 39944624, 2025). "The results of this study provide a thorough examination of novel compounds found to inhibit BACE1, a crucial target in the management of Alzheimer’s disease (AD)." (PMID 40117242, 2025).
Alzheimer disease (continued). "The inhibition of BACE1 can reduce β-amyloid generation and has therefore been extensively studied as a potential therapeutic strategy for Alzheimer’s disease and related neurodegenerative disorders." (PMID 40795814, 2025). "The similar strategy was used upon the siRNA-mediated knockdown of the beta-site APP cleaving enzyme β-secretase 1 (BACE1), a therapeutic target in Alzheimer’s disease." (PMID 40430932, 2025). "Beta-site amyloid precursor protein cleaving enzyme (BACE-1), also known as β-secretase involved in Alzheimer’s pathogenesis, is a less explored target by the medicinal chemist for treating Alzheimer’s disease." (PMID 41103911, 2025). "In contrast, the study of lncRNA BDNF-AS revealed that through the regulation of the miR-9-5p/BACE1 pathway, it enhanced neurotoxicity in Alzheimer’s disease by promoting the formation of amyloid plaques." (PMID 41245147, 2025). "Progressin this field will continue to rely on integrated approaches thatunite synthetic chemistry, structural insights, and pharmacologicalevaluation to unlock the therapeutic potential of BACE-1 inhibitionin Alzheimer’s disease." (PMID 40852238, 2025). "Elevated BACE1 levels in the brains of Alzheimer’s disease (AD) patients implicate that dysregulated BACE1 expression is crucial to AD pathogenesis." (PMID 40587559, 2025). "Subsequently, lncRNA NEAT1 was shown to act as a promoting factor for Alzheimer’s disease progression via modulation of the miRNA-124/BACE1 axis." (PMID 41245147, 2025). "Alzheimer’s Disease (AD): EVs loaded with siRNA targeting pathological proteins (e.g., BACE1 or tau) delivered via RVG-functionalized exosomes reduced amyloid burden, attenuated neuroinflammation, and improved cognitive performance in transgenic mouse models." (PMID 41155971, 2025). "In Alzheimer's disease models, icariin ameliorates cognitive deficits by modulating multiple pathways, including BACE-1, NO/cyclic guanosine monophosphate (cGMP), Wnt/Ca2+, and PI3K/Akt signaling." (PMID 40546602, 2025). "BACE1 is a key therapeutic target for reducing Aβ generation and potentially slowing the progression of Alzheimer’s disease." (PMID 40117242, 2025). "In conclusion, the tubular form withthe stopper shows great potential for Alzheimer’s disease treatment,as it blocks the entrance cavity of the AChE active pocket and enhancesthe stability of the inactive BACE-1 enzyme." (PMID 40787376, 2025). "For example, beta-secretase 1(BACE1)-AS, BC200, and NEAT1 have been associated with Alzheimer’s disease (AD)." (PMID 39920595, 2025). "The predicted BBB penetration (QPlogBB) values indicated that VERMOD-33 (0.273) has the highest potential for CNS access, which is desirable for BACE1 inhibition in Alzheimer’s disease therapy." (PMID 41465568, 2025). "The resulting BACE1 siRNA-loaded EVs effectively down-regulated BACE1 mRNA in the mouse brain and alleviated Alzheimer’s disease symptoms." (PMID 40400306, 2025). "BACE1 is a crucial target in Alzheimer’s disease and holds significance in aging, diabetes, hypertension and cancer." (PMID 39944624, 2025). "But circRNA AXL increased neuronal damage and neuroinflammation via miRNA-328’s effect on BACE1 in Alzheimer’s disease." (PMID 41245147, 2025). "β-site amyloid precursor protein cleaving enzyme 1 (BACE1) is a central therapeutic target in Alzheimer’s disease, as it catalyzes the rate-limiting step in amyloid-β production." (PMID 41465568, 2025). "In conclusion, thetubular form with a stopper group shows great potential for the treatmentof Alzheimer’s disease, as it blocks the entrance cavity ofthe AChE active pocket for the substrate and increases the stabilityof the inactive BACE-1 enzyme." (PMID 40787376, 2025). "BACE1 is a critical enzyme in the production of amyloid-beta (Aβ), which is significant in Alzheimer’s disease (AD)." (PMID 40134534, 2025).
Alzheimer disease (continued). "Specific BACE1 inhibitors have also been developed, and some of the inhibitors have been evaluated in clinical trials of Alzheimer’s disease." (PMID 38248330, 2024). "In conclusion, we have performed a detailed phylogenetic and functional biochemical examination of the evolutionary history of BACE1, the rate-limiting protease responsible for liberating the Aβ peptide from amyloid precursor protein in Alzheimer’s disease." (PMID 38785802, 2024). "In the case of Alzheimer’s disease, the expression of the BACE1 enzyme has been found to be significantly elevated in cortex and hippocampus brain regions, thereby generating Aβ protein." (PMID 39224568, 2024). "They highlight the importance of integrating various computational tools, structural information, and experimental validation in the drug discovery process, particularly for targets like BACE-1 involved in Alzheimer’s disease." (PMID 38999999, 2024). "BACE2, along with BACE1, has been extensively studied in the context of Alzheimer’s disease, as both enzymes are responsible for processing APP into neurotoxic Aβ peptides." (PMID 39109301, 2024). "Studies have shown both a significant build-up of β-secretase (BACE1) amount and an increase in its gene expression in the brain tissues of patients with Alzheimer’s disease." (PMID 39267722, 2024). "Lastly, while G-Bro shows promise in inhibiting BACE1 and preventing Aβ aggregation, the interaction with other pathways involved in Alzheimer’s disease pathology, such as tau aggregation or neuroinflammation, was not investigated in this study." (PMID 39684923, 2024). "Tan X., Luo Y., Pi D., Xia L., Li Z., Tu Q. MiR-340 reduces the accumulationof amyloid-β through targeting BACE1 (β-site amyloidprecursor protein cleaving enzyme 1) in Alzheimer’s disease." (PMID 38680184, 2024). "This deposition occurs by APP cleavage by BACE1 enzyme at the N-terminal region which produces membrane-bound APP-C-terminal fragments (CTFs) which are early markers for Alzheimer’s disease." (PMID 38572181, 2024). "BACE1 is responsible for generating β-amyloid peptides which form plaques in the brains of Alzheimer’s disease (AD) patients resulting in the neuronal dysfunction associated with that disease." (PMID 39194679, 2024). "Potent and specific inhibitors for BACE1 are known for the clinical treatment of Alzheimer’s disease." (PMID 38248330, 2024). "This study employs advanced network and graph theory tools to comprehensively analyze the structural and biochemical properties of BACE-1 inhibitors, which play a critical role in the treatment of Alzheimer’s disease." (PMID 38999999, 2024). "Important GTPases include Rab5 and Rab7, which are upregulated in Alzheimer’s disease, and Rab11, which is needed for axonal sorting of BACE-1." (PMID 38276010, 2024). "Specifically, they employed brain-targeted exosomes to administer BACE1 siRNA, with the aim of addressing Alzheimer’s disease." (PMID 38393218, 2024). "BACE-1 is an aspartyl protease enzyme that plays a pivotal role in the pathogenesis of Alzheimer’s disease by catalyzing the first step in the production of amyloid-beta peptides." (PMID 38999999, 2024). "Inhibiting BACE-1 has been identified as a promising therapeutic strategy to reduce amyloid-beta levels and potentially slow or prevent the progression of Alzheimer’s disease." (PMID 38999999, 2024). "APLP1, APLP2, and APP are well-established substrates of β-site amyloid precursor protein cleaving enzyme 1 (BACE1), playing crucial molecular roles in Alzheimer’s disease." (PMID 38370359, 2024). "Third, it is still uncertain and remains a matter of ongoing research as to when the administration of BACE1 inhibitors will provide optimal results, with more recent results indicating a more prophylactic benefit at early stages of Alzheimer’s disease." (PMID 38572181, 2024). "With another secretase, PS/γ-secretase, BACE1 has been studied as a target for the treatment of Alzheimer’s disease." (PMID 38248330, 2024).
Alzheimer disease (continued). "The β-secretase β-site APP cleaving enzyme (BACE1) is a central drug target for Alzheimer’s disease." (PMID 38888964, 2024). "The inhibitory activities of the herbal extracts were assessed on the key enzymes that control the occurrence of some NCDs including type II diabetes (T2DM) (α-amylase and α-glucosidase), Alzheimer’s disease (AChE, BChE, and BACE-1) and hypertension (ACE)." (PMID 38066118, 2023). "For the enzymes involved in Alzheimer’s disease (AChE, BChE, and BACE-1), DL exhibited the highest C score of 0.891." (PMID 38066118, 2023). "For example, S1P was found to bind and activate β-site amyloid precursor protein (APP) cleaving enzyme-1 (BACE1) leading to an increase in amyloid-β peptide (Aβ) production which is involved in the pathogenesis of Alzheimer’s disease (AD)." (PMID 37345069, 2023). "A multi-target activity 3D-QSAR model against acetylcholinesterase (AChE), serotonin transporter (SERT), beta-secretase 1 (BACE1) and glycogen synthase kinase-3 (GSK3β) was built to towards new therapeutics for Alzheimer’s disease." (PMID 36770990, 2023). "Due to BACE1′s critical role as the initiating enzyme in amyloid-beta production, it has been selected as a prime target for slowing the progression of Alzheimer’s disease by lowering amyloid-beta levels in the brain." (PMID 37444065, 2023). "In a study on the SAMP8 mouse model of Alzheimer’s diseases, the expression level of miR-340 was decreased, while BACE1 was increased, indicating the opposite correlation between the levels of miR-340 and BACE1 in the hippocampus of AD mice." (PMID 37727513, 2023). "The enzyme beta-site amyloid precursor protein cleaving enzyme-1 (BACE1) is involved in the aberrant synthesis of the amyloidogenic peptide Aβ, and is one of the primary causes of Alzheimer's disease (AD)." (PMID 38106650, 2023). "DL controlled Alzheimer’s disease progression through the cholinergic enzymes (AChE and BChE) and the β-amyloid forming enzyme (BACE-1)." (PMID 38066118, 2023). "Two neurotransmitter-degrading enzymes (AChE and BChE) and the β-amyloid formation enzyme (BACE-1) were investigated to control Alzheimer’s disease." (PMID 38231711, 2023). "Overall, this study provides insights into the potential use of in silico methods for drug repurposing and identification of new candidates for the treatment of Alzheimer’s disease, especially those targeting BACE-1." (PMID 37175873, 2023). "Natural substances such as flavones and flavonoids have different biological activities, including AChE and BACE-1 (Beta-secretase 1) inhibition, so they are attractive targets for Alzheimer’s disease." (PMID 38067639, 2023). "Although trial was terminated in 2018, this drug did prove that BACE1 inhibitors need to be administered several years before symptoms of Alzheimer’s disease are apparent." (PMID 37444065, 2023). "Since the first report of type 1 melatonin receptor (Mt1) and β-secretase 1 (Bace1) for the regulation of Aβ production, targeting Mt1 and Bace1 has been considered a powerful therapeutic approach for Alzheimer’s disease." (PMID 36833410, 2023). "Sulforaphane showed its neuroprotective effect in animal and cell models of neurodegenerative condition, and it can activate Nrf2 to inhibit BACE1 mRNA expression and reduce Aβ production in the prevention of Alzheimer’s disease." (PMID 36829795, 2023). "In molecular docking studies, the naturally occurring compounds hecogenin, naringin 6” malonate, procyanidin B2 and kaempferol-dirhamnoside illustrated promising binding affinity towards the BACE-1 protein receptor for Alzheimer’s disease." (PMID 37367915, 2023). "Nogo-A affected amyloid deposition and the formation of dystrophic neurites by negatively regulating BACE1 activity, thereby affecting the metabolism of Aβ and triggering the occurrence and development of Alzheimer's disease." (PMID 36323241, 2023).